PDE7B (phosphodiesterase 7B)
Description:
Hydrolyzes the second messenger cAMP, which is a key regulator of many important physiological processes. May be involved in the control of cAMP-mediated neural activity and cAMP metabolism in the brain.
Synonyms: bA472E5.1
Tractability: Small molecule: an approved drug acts on it; a high-quality ligand is known; it belongs to a druggable protein family. PROTAC: ubiquitination databases record sites on it; a small molecule that binds it is known.
Target class: Phosphodiesterase; Phosphodiesterase 7B; Phosphodiesterase 7; Enzyme
Gene: Protein-coding gene on chromosome 6 (135,851,701 to 136,195,574, forward strand). Ensembl gene ENSG00000171408.
Subcellular location (Human Protein Atlas): Nucleoplasm
Pathways (Reactome):
Signal Transduction: G alpha (s) signalling events
Gene Ontology:
Molecular function: 3',5'-cyclic-AMP phosphodiesterase activity; 3',5'-cyclic-GMP phosphodiesterase activity; 3',5'-cyclic-nucleotide phosphodiesterase activity; cyclic-nucleotide phosphodiesterase activity; phosphoric diester hydrolase activity
Biological process: chemical synaptic transmission; negative regulation of cAMP/PKA signal transduction; signal transduction; cAMP catabolic process
Cellular component: cytosol; synapse
Genetic constraint (gnomAD): Loss-of-function variants: 8 observed, 18.22 expected, observed/expected ratio (o/e) 0.44, 90% interval 0.26 to 0.79. The upper end of that interval is the gene's LOEUF score, 0.79, which puts it in group 3 of 6, group 1 being the genes least tolerant of losing a copy. Missense variants: 237 observed, 293.36 expected, observed/expected ratio (o/e) 0.81, 90% interval 0.73 to 0.9. Synonymous variants: 106 observed, 113.62 expected, observed/expected ratio (o/e) 0.93, 90% interval 0.8 to 1.1.
Homologues: Orthologues: chimpanzee PDE7B (94% identical), macaque PDE7B (94% identical), pig PDE7B (90% identical), dog PDE7B (89% identical), rabbit PDE7B (89% identical), mouse Pde7b (88% identical), guinea pig PDE7B (88% identical), rat Pde7b (87% identical), tropical clawed frog pde7b (78% identical), Caenorhabditis elegans pde-3 (22% identical), Drosophila melanogaster Pde8 (22% identical), Drosophila melanogaster Pde11 (21% identical), and 1 more. Paralogues in human: PDE7A (57% identical), PDE4A (28% identical), PDE4B (27% identical), PDE4D (27% identical), PDE4C (26% identical), PDE3B (25% identical), PDE1B (25% identical), PDE1C (25% identical), PDE1A (24% identical), PDE3A (24% identical), PDE8A (24% identical), PDE8B (24% identical), and 8 more.
Diseases named in the same sentence as PDE7B in open-access papers:
PDE7B is named in the same sentence as 36 diseases in open-access papers, as found by Europe PMC text mining. Sharing a sentence is not in itself a finding about the gene and the disease. The quoted sentences say what the papers report.
breast carcinoma (6 papers, 2018 to 2024). "Inducing cellular cAMP level by inhibiting PDE7B expression or activity has been reported to trigger apoptosis in chronic lymphocytic leukemia and breast cancer." (PMID 32922506, 2020). "Additionally, the inhibition of PDE7B enhances the sensitivity of breast cancer cells to certain chemotherapeutic agents, such as microtubule-targeting drugs, thereby improving the effectiveness of chemotherapy." (PMID 39640266, 2024).
chronic lymphocytic leukemia (6 papers, 2014 to 2024). "PDE7B is also upregulated in chronic lymphocytic leukemia and set cell lymphoma and serves as a factor in the inferior survival of patients with these cancers." (PMID 38778317, 2024). "In hematological malignancies, primary chronic lymphocytic leukemia patient samples were found to have PDE7B overexpression and noted to be sensitive to PDE7 inhibition in a cAMP‐dependent manner." (PMID 32749766, 2020). "PDE7 inhibitors selectively induce apoptosis in chronic lymphocytic leukemia cells due to PDE7B overexpression." (PMID 32922506, 2020).
glioblastoma (6 papers, 2014 to 2024). The most malignant astrocytic tumor (WHO grade IV). "The expression of PDE7B was seen prominently in putamen and caudate nucleus of human brain.PDE7B overexpression showedtumor growth in glioblastoma animal model studies." (PMID 32405171, 2020). "The interaction between glioblastoma and endothelial cells leads to elevated PDE7B expression, which promotes tumor growth and aggressiveness." (PMID 32922506, 2020). "PDE7B is another cAMP specific phosphodiesterase that is frequently upregulated in glioblastoma (GBM) and is negatively correlated with survival." (PMID 26283963, 2015). "PDE7B plays a crucial role in the tumor microenvironment, and the presence of endothelial cells may promote the expression of PDE7B, thereby influencing the occurrence and development of glioblastoma." (PMID 39640266, 2024). "The higher level of PDE7B occurs in most glioblastoma cases and harms survival." (PMID 32922506, 2020).
schizophrenia (4 papers, 2014 to 2024). A major psychotic disorder characterized by abnormalities in the perception or expression of reality. "In addition, PDE7B can also play a role in asthma, schizophrenia, Alzheimer’s disease and other diseases." (PMID 39640266, 2024). "Among them, the mutations in Rarb could cause intellectual disability with progressive motor impairment, and Pde7b plays an important role in schizophrenia and dopaminergic cell death." (PMID 36142685, 2022). "Interestingly, the remaining genes in which immobilization (Immo+FC) had induced changes in expression seem to be involved in immune response (Lbp and Lnc2), anxiety behavior and schizophrenia (Pde7b), corticosterone homeostasis, and steroid transportation (Lcn2 and Soat1)." (PMID 30705647, 2018).
hepatocellular carcinoma (3 papers, 2024 to 2025). A malignant tumor that arises from hepatocytes. "Restoring PDE7B expression in hepatocellular carcinoma cell lines inhibited tumor proliferation and metastasis by regulating the EMT process and inhibition of the PI3K/AKT signaling pathway." (PMID 41179677, 2025). "This investigation highlights the correlation between decreased PDE7B expression in hepatocellular carcinoma and unfavorable prognosis." (PMID 39640266, 2024). "Our current findings suggest that PDCD1 is upregulated in hepatocellular carcinoma and shows an inverse correlation with PDE7B expression." (PMID 39640266, 2024). "Through transcriptome sequencing analysis, we identified PDCD1 as a potential target of PDE7B in hepatocellular carcinoma." (PMID 39640266, 2024). "PDE7B is conspicuously reduced in tissues and cells of hepatocellular carcinoma, showing a connection with an unfavorable prognosis." (PMID 39640266, 2024). "Real-time fluorescence quantitative polymerase chain reaction (qRT-PCR) and Western blotting were employed to analyze the expression of PDE7B in hepatocellular carcinoma tissues and cells." (PMID 39640266, 2024). "The research we conducted reveals that PDE7B, a gene with minimal levels of activity in hepatocellular carcinoma, possesses the capacity to inhibit the proliferation, invasion, and migration of HCC cells." (PMID 39640266, 2024). "Our study demonstrated that PDE7B, which functions as a tumor suppressor gene, significantly contributes to the initiation and progression of hepatocellular carcinoma." (PMID 39640266, 2024). "PDE7B can impact the development of hepatocellular carcinoma by adjusting mechanisms related to oxidative stress." (PMID 39640266, 2024). "This suggests that the increased expression of PDE7B, as a potential oncogene, may inhibit the EMT process of hepatocellular carcinoma cells by suppressing the PI3K-AKT pathway, and thus play a tumor-suppressive role." (PMID 38778317, 2024).
glioma (2 papers, 2014 to 2020). A benign or malignant brain and spinal cord tumor that arises from glial cells (astrocytes, oligodendrocytes, ependymal cells). "Fluorescence molecular tomography (FMT) was used to quantify the uptake of tumor-targeted and passive NIR fluorescent imaging agents in orthotopic glioma (U87-GL-GFP PDE7B H217Q cells) tumor model." (PMID 32112540, 2020). "Therefore future work should focus on taking specific inhibitors of PDE7B from the autoimmune studies and determining their efficacy in blocking glioma growth in vitro and in vivo with the hope of translating these findings to the clinic as quickly as possible." (PMID 25203500, 2014).
liver cancer (2 papers, 2024). An epithelial or non-epithelial malignant neoplasm that arises from the liver. "The DNA methylation level of PDE7B in liver cancer was found to be significantly higher than that of controls, especially in cg14623715, cg3984009 and cg041521966 locus." (PMID 38778317, 2024). "According to our trials relating to oxidative stress, PDE7B appears to control cell death in liver cancer cells by impacting the production of reactive oxygen species." (PMID 39640266, 2024). "The biological role of PDE7B in HCC was investigated by both overexpressing and knocking down PDE7B in liver cancer cell lines." (PMID 39640266, 2024). "Inhibiting PDE7B boosts the growth, movement, and infiltration of liver cancer cells, while its increased expression has the reverse impact." (PMID 39640266, 2024). "The effect of PDE7B can be eliminated by reducing ROS levels via the use of NAC, indicating that increased ROS levels serve as a key marker for the PDE7B-mediated inhibition of liver cancer cell apoptosis." (PMID 39640266, 2024). "We hypothesized that PDE7B may also regulate liver cancer progression via the PI3K/AKT signaling pathway." (PMID 39640266, 2024). "Moreover, we discovered that liver cancer clinical indicators are correlated with PDE7B expression and that HCC patients with elevated PDE7B expression have an improved prognosis." (PMID 39640266, 2024). "Hence, we analyzed the antitumor effects of PDE7B in liver cancer." (PMID 39640266, 2024).
Obesity (2 papers, 2015 to 2022). Accumulation of substantial excess body fat. "However, 4/11 have known or potential roles in obesity, MYO1C, PLIN4, PARD3 and PDE7B." (PMID 25651499, 2015).
astrocytomas (1 paper, 2014). "Stratification of all astrocytomas based on PDE7B expression two-fold above or below the median level of expression revealed a striking correlation with survival." (PMID 25203500, 2014). "To determine whether levels of PDE7B expression are prognostic in GBM we first examined the National Cancer Institute’s (NCI) Rembrandt Database for all grades of astrocytoma." (PMID 25203500, 2014).
brain cancer (1 paper, 2020). A primary or metastatic malignant neoplasm affecting the brain. "Stereotactically implanted brain cancer cells expressing a bioluminescent reporter (U87-GL-GFP PDE7B H217Q cells) allowed for facile longitudinal localization and monitoring of tumor burden using a commercialBLI system, and FMT was used to quantify the delivery of ICG and LS301 to tumors." (PMID 32112540, 2020).
breast tumor (1 paper, 2020). "This study implicates that EA11 prevents breast tumor development by interfering with the miR-200c-PDE7B/PD-L1-AKT/MAPK axis." (PMID 32922506, 2020). "In conclusion, our study demonstrated that EA11 could suppress breast tumor development by interfering with the miR-200c-PDE7B/PD-L1-AKT/MAPK axis." (PMID 32922506, 2020).
Cognitive impairment (1 paper, 2020). Abnormal cognition is characterized by deficits in thinking, reasoning, or remembering. "The PDE7B gene encodes 3'5'-cyclic nucleotide phosphodiesterase (PDE) and a known target in cognitive impairments." (PMID 32405171, 2020). "We report the binding features of aspirin with the PDE7B enzyme in the context of cognitive impairments for further consideration." (PMID 32405171, 2020).
coronary heart disease (1 paper, 2021). "Also, dipyridamole, a 3′,5′-cyclic phosphodiesterase inhibitor, targets PDE7B and current clinical trials are testing therapies based on dipyridamole for diseases such as stroke, coronary heart disease, ischemia reperfusion injury, and internal carotid artery stenosis." (PMID 33627673, 2021).
depression (1 paper, 2022). "In most of the top models, a consistent dysregulation of MAP kinase pathway was identified and the genes NR4A1, BDNF, ARC, EGR2, and PDE7B were consistently downregulated as in humans with depression." (PMID 34997033, 2022).
glaucoma (1 paper, 2018). Increased pressure in the eyeball due to obstruction of the outflow of aqueous humor. "Thus, PDE7B through its effect on the regulation of cAMP levels may contribute to aqueous humor outflow or support RGC survival, functions that have important consequences in the pathogenesis of glaucoma." (PMID 29891935, 2018).
leukemia (1 paper, 2019). A malignant (clonal) hematologic disorder, involving hematopoietic stem cells and characterized by the presence of primitive or atypical myeloid or lymphoid cells in the bone marrow and the blood. "And we detected a significantly higher expression level of PDE7B in the leukemia stem cell (LSC) positive group." (PMID 31740742, 2019). "The high expression of PDE7B gene has a significant correlation with leukemia stem cells." (PMID 31740742, 2019). "PDE7B is a specific hydrolase for cAMP which is critical for leukemia cell differentiation." (PMID 31740742, 2019). "Therefore, we can speculate that high expression of PDE7B may lead to a decrease in intracellular cAMP levels, which in turn prevents leukemia cells from further differentiation and maturation." (PMID 31740742, 2019). "Therefore, it is not difficult to speculate that PDE7B, as a specific hydrolase of cAMP, may play an important role in the development of leukemia cells by regulating the concentration of cAMP." (PMID 31740742, 2019).
lymphoma (1 paper, 2019). A malignant (clonal) proliferation of B- lymphocytes or T- lymphocytes which involves the lymph nodes, bone marrow and/or extranodal sites. "cAMP promotes growth arrest and/or apoptosis of various types of lymphoma, particularly CLL, and PDE7 inhibitors can increase cAMP concentration and kill CLL cells, which is suggesting that PDE7B may act as a therapeutic target in CLL." (PMID 31740742, 2019). "And then it has been suggested that cAMP can inhibit the growth of various types of lymphoma (especially CLL), while PDE7 inhibitors (nonselective for PDE7A and PDE7B) can kill CLL cells by increasing cAMP concentration, which may be a useful treatment for such diseases." (PMID 31740742, 2019).
myxoma (1 paper, 2024). A benign soft tissue neoplasm characterized by the presence of spindle and stellate cells, lobulated growth pattern, and myxoid stroma formation. "One of the most notable findings was significant upregulation of cyclic nucleotide phosphodiesterase (PDE) gene families, including PDE3A, PDE1A, PDE7B, and PDE10A in myxoma cells." (PMID 39090109, 2024).
pulmonary fibrosis (1 paper, 2023). Chronic progressive interstitial lung disorder characterized by the replacement of the lung tissue by connective tissue, leading to progressive dyspnea, respiratory failure, or right heart failure. "According to the results of qRT-PCR, the expression levels of ENPP3, PDE7B, and ENTPD1 were elevated, while the expression levels of PNMT, GPX3, and POLR3H were decreased in the lung tissues of bleomycin-induced pulmonary fibrosis mice compared with the sham group." (PMID 36923791, 2023).
tumor (10 papers, 2014 to 2025). "Moreover, through a combined WGBS and RNA sequencing analysis, we determined that PDE7B expression, a potential methylation-related tumor suppressor, was downregulated and associated with HCC prognosis." (PMID 38778317, 2024). "In our investigation, compared with adjacent paracancerous tissue, tumor tissue from HCC patients exhibited a noteworthy decrease in PDE7B mRNA and protein levels." (PMID 39640266, 2024). "Compared to that in the control group, PDE7B expression in Grade 1, 2, and 3 tumors was significantly lower, depending on the tumor grade." (PMID 39640266, 2024). "In the future, we will explore the targeting of PDE7B in cancer therapy and conduct further preclinical and clinical studies to validate its role in tumor progression." (PMID 39640266, 2024). "Tumor weight was assessed after 4 weeks by removing the subcutaneous tumor and measuring the tumor volume every 3-4 days in cells overexpressing PDE7B." (PMID 39640266, 2024). "The expression of PDE7B in tumor tissues (n = 84) and neighbouring normal tissues (n = 84) was detected using immunohistochemistry, and the tissues were obtained from the Affiliated Hospital of Guilin Medical College." (PMID 38778317, 2024). "The results of qRT-PCR analysis and western blot assay showed that PDE7B mRNA and protein levels were reduced in tumor tissues compared to normal tissues." (PMID 33817314, 2021). "Taken together, our results verified that circ_WWC3 exerted the tumor-suppressive function in OS through repressing proliferation and metastasis and promoting apoptosis, possibly by modulating miR-421/PDE7B axis." (PMID 33817314, 2021). "We recently reported induction of phosphodiesterase 7B in GBM tumor cells through direct contact-mediated effects of endothelial cells in this same co-culture model." (PMID 26286961, 2015). "Consistent with the BLI and survival data, histological analysis revealed that tumor size was consistently greater in the PDE7B WT tumor group than the PDE7B H217Q tumor group." (PMID 25203500, 2014). "This pattern of growth is evident in the analysis of PDE7B H217Q tumors where a clear boundary is evident between the tumor and the surrounding brain." (PMID 25203500, 2014). "Strikingly, PDE7B WT tumors exhibited a more aggressive tumor phenotype than is normally seen with U87 xenografts." (PMID 25203500, 2014). "PDE7B overexpression resulted in the expansion of a stem-like cell subpopulation in vitro and increased tumor growth and aggressiveness in an in vivo intracranial GBM model." (PMID 25203500, 2014). "On the contrary, overexpression of PDE7B inhibited tumor proliferation and metastasis in vitro." (PMID 38778317, 2024). "In addition, PDE7B overexpression was found to inhibit the proliferation, migration and invasion of HCC cells in vitro, suggesting that PDE7B has a tumor-suppressive role in HCC." (PMID 38778317, 2024). "In conclusion, the present study provides evidence that PDE7B has a tumor-suppressive role in HCC and that its downregulation is associated with hypermethylation of its promoter region with the ability to regulate the EMT process in HCC through the PI3K-AKT pathway." (PMID 38778317, 2024). "In brief, PDE7B overexpression inhibits tumor development in vivo." (PMID 39640266, 2024). "In vivo experiments confirmed that overexpression of PDE7B inhibits tumor growth." (PMID 39640266, 2024). "In this study, we hypothesize that PDE7B impacts tumor progression through the cAMP/PKA/CREB regulatory axis." (PMID 39640266, 2024). "However, more recent studies have shown the opposite, indicating that PDE7B is downregulated in renal tumors and has a tumor-suppressive role." (PMID 38778317, 2024). "Increased expression of PDE7B was observed in a subset of tumor cells with enhanced tumor initiating capacity, and overexpression of PDE7B in a U87 intracranial xenograft model of GBM transformed the typical circumscribed pattern of intracranial U87 growth into a highly invasive one." (PMID 26283963, 2015).